MRPS18AP1 (mitochondrial ribosomal protein S18A pseudogene 1)
Gene: Processed pseudogene on chromosome 3 (48,256,350 to 48,256,938, reverse strand). Ensembl gene ENSG00000229759.
Diseases named in the same sentence as MRPS18AP1 in open-access papers:
MRPS18AP1 is named in the same sentence as 1 disease in open-access papers, as found by Europe PMC text mining. Sharing a sentence is not in itself a finding about the gene and the disease.
MRPS18AP1 shares sentences with these, for which no sentence is quoted: skin cutaneous melanoma (1 paper).